AXL (AXL receptor tyrosine kinase)
Diseases named in the same sentence as AXL in open-access papers (continued):
Sharing a sentence is not in itself a finding about the gene and the disease.
tumor (continued). "We determined that AXL interacted with other molecules, including EGFR and HER3, and maintained survival of tumor cells exposed to osimertinib." (PMID 30651547, 2019). "The proto-oncogenic potential of AXL and MERTK was identified immediately upon their cloning from tumor cell lines." (PMID 31775787, 2019). "While our studies provide confirmation that AXL is upregulated following TKI resistance; further exploration is required to determine if the tumor and metastasis-limiting effects of sitravatinib are the result of TAM family inhibition." (PMID 31369645, 2019). "In the tumor microenvironment, IL32 expression is highly correlated with genes related to T cell infiltration, and also positively correlates with high AXL/low MITF dedifferentiated gene signature." (PMID 30953519, 2019). "In this study, the AXL and GAS6 gene expression differences between tumor stages were statistically significant." (PMID 31700829, 2019). "We have therefore now evaluated AXL and GAS6 levels in both tumor tissue and plasma as well as their relation to clinical course in EGFR‐mutated NSCLC patients before treatment with and after the development of resistance to EGFR‐TKIs." (PMID 31419057, 2019). "AXL, on the other hand, is an interesting ECM sensing receptor involved in both tumor cell metastasis and immune cell function." (PMID 30388137, 2018). "TAM receptors AXL and MERTK are also known as protooncogenes: they are highly expressed in numerous tumor cells." (PMID 30140167, 2018). "COL1 is found extensively in tumor stroma, and when combined with certain other common tumor microenvironment proteins (i.e., COL6A3, OPN, and IL-8) the frequency of AXL-expressing cells significantly increased." (PMID 29719832, 2018). "In 3D spheroid culture, the activation of the TAM‐PDK‐RSK‐mTOR pathway proves crucial following treatment with AXL/MET inhibitor BMS777607, when the self‐sustaining tumor cells react with TAM‐RSK hyperactivation and enhanced SRC‐AKT‐mTOR signaling." (PMID 28675785, 2017). "The tumor-promoting properties of AXL can be stimulated by the TAM ligand GAS6, which binds to AXL with highest affinity if co-expressed within tumor cells." (PMID 28118606, 2017). "Next, we tested cabozantinib (CB), a TKI that targets VEGF receptors (VEGFRs), MET, AXL, TIE-2, RET and other RTKs involved in tumor development and progression through angiogenesis, invasiveness, metastasis, anti-apoptosis and drug resistance." (PMID 29206199, 2017). "Expression levels of miR‐34a and target genes AXL and MMP14 are closely correlated among each other and clearly separate tumor from adjacent normal tissue." (PMID 28596300, 2017). "As overexpression of AXL/GAS6 can contribute to tumor invasion, metastasis especially to the brain, and drug resistance against chemotherapy and targeted therapies in NSCLC, the AXL/GAS6 pathway can be promising therapeutic target for clinical inhibition." (PMID 28551766, 2017). "Paired tissue analysis in 3 patients identified ARG, AXL, TYRO3 and ZAP70 as increased in tumor relative to adjacent normal." (PMID 28423512, 2017). "Additional in vivo studies have demonstrated that blocking AXL can suppress the growth of FLT3-ITD AML, decrease tumor size, and block the activation of cellular survival pathways while upregulating the apoptotic pathway." (PMID 28516360, 2017). "The addition of macitentan to the BRAF inhibitor reduced the expression of EDNRA within the tumours, suggesting that through its affinity for EDNRA macitentan targets the AXL/EDNRA‐expressing cells." (PMID 28606996, 2017). "Independently of the AXL/GAS6 system, tumor cells develop a heterogeneous setup of resistance mechanisms to cancer drug treatments." (PMID 28675785, 2017). "The results showed that AXL and GAS6 expressions are primarily localized both at the cytoplasmic membrane and within the cytoplasm of tumor cells, respectively." (PMID 28551766, 2017).
tumor (continued). "Activated AXL subsequently activates the MAPK/ERK and PI3K/AKT signaling pathways, leading to tumor growth and invasion." (PMID 29097911, 2017). "Moreover, because the EDN1‐induced paracrine signalling has the potential to support both MITF‐high and AXL‐high phenotypes in acquired resistant tumours, targeting the EDN1‐EDN receptor axis could reduce the complexity seen in patients treated with MAPK inhibitor at time of progression." (PMID 28606996, 2017). "The top 10 unpaired normal (n=4 samples) to tumor (n=11 samples) increased protein kinases were SYK, ZAP70, ARG (ABL2), ERBB3, ABL, TEC, MER (MERTK), AXL, EGFR and ERBB2." (PMID 28423512, 2017). "Concordantly, TUNEL and caspase 3/7 profiling revealed activated PSCs protect tumor cells from apoptosis and sensitize tumor cells to reciprocal node inhibitors (IGF1R/AXL and AKT)." (PMID 27087446, 2016). "In agreement, cell-specific analysis of PDA proliferation in homo and heterocellular cultures revealed increased tumor cell proliferation under heterocellular conditions (via SHH, IGF1R/AXL, and AKT activity)." (PMID 27087446, 2016). "Tumor genotype was established using Sequenom Mass ARRAY; EGFR, PTEN, cMET and AXL expression was assessed by immunohistochemistry, circulating markers of EGFR activation (TGF-α, amphiregulin, epiregulin, EGFR ECD) by ELISA and EGFR, MET copy number by FISH." (PMID 27028852, 2016). "Simple pharmacological perturbation of reciprocal nodes (e.g., IGF1R, AXL, AKT, etc.)in existing PDA GEMMs will in principle affect all cell types (e.g., tumor cells, PSCs, immune cells) and cannot provide axis-specific information in vivo." (PMID 27087446, 2016). "Reciprocal signaling regulates tumor cell proliferation and apoptosis and increases mitochondrial capacity via an IGF1R/AXL-AKT axis." (PMID 27087446, 2016). "This is consistent with previous findings that AXL stabilization is an oncogenic mechanism for RARRES1, and with our own findings that RARRES1 is tumor suppressive in TNBC." (PMID 27286452, 2016). "After gefitinib treatment, the tumor volumes of MDA-MB-231/E1A/AXL-injected mice were higher than those of MDA-MB-231/E1A/Ctrl-injected mice, suggesting that downregulation of AXL is essential for E1A-mediated sensitization of EGFR-TKI." (PMID 27590506, 2016). "In conclusion, our work demonstrated miR-432 plays a tumor-suppressive role in LAD and its function is mainly mediated by its targets, E2F3 and AXL." (PMID 26942465, 2016). "Inhibition of AXL reversed chemoresistance by decreasing expression of the anti-apoptotic proteins BCL-2, BCL-XL, MCL1 and survivin in tumor cells and activated pro-apoptotic proteins BAD, BAX, BCL-2, BAK and PUMA." (PMID 26328272, 2015). "On the other hand, subpopulations of AXL+/WNT5A+ MITF‐negative cells can escape therapy and thus will be able to re‐establish tumour growth." (PMID 25818589, 2015). "In this study, we determined that AXL is expressed in a subset of WDLPS, DDLPS, and PLS patient tumor samples." (PMID 26573603, 2015). "In this patient we found strong expression of AXL in the excised nodular neurofibroma, while the plexiform/MPNST tumor from the same patient had lower levels; however, it was still higher than that of the normal sciatic nerve." (PMID 25551830, 2014). "Treatment with the AXL inhibitor MP470 (Amuvatinib) reversed EMT and thereby reduced tumor growth, downregulated NF-kB pathway activity and led to restoration of chemosensitivity in murine BCSCs and mesenchymal normal human mammary epithelial cells." (PMID 25337673, 2014). "Expressed genes found in both the tumor group and the NPC with antitumor effect were Camk2, CD81, Kai1, TPT1 and AXL." (PMID 19558675, 2009). "A comparison of these with the 683 KPTN tumor–upregulated genes revealed 130 consistently upregulated genes, including ECM components (COL4A1, COL4A2, COL12A1, VCAN, etc.)and YAP targets (ANKRD1, AXL, CYR61, F3)." (PMID 41480763, 2026).
tumor (continued). "At higher doses, LY2801653 also affected tumors lacking MET/AXL expression by reducing angiogenesis and M2 macrophages in the tumor microenvironment." (PMID 41011010, 2025). "Whilst tilvestamab did not lead to objectively measurable responses irrespective of AXL expression status, our exploratory analyses of paired tumour biopsy specimens showed reduction in AXL protein expression, which led to AKT inhibition and AMPK activation." (PMID 40696160, 2025). "While most tumor meta-programs exhibited melanocytic differentiation (high MITF and CTNNB1), two meta-programs-Respiration and Stress-expressed dedifferentiation markers including AXL, SOX9, EGFR and NGFR." (PMID 40890106, 2025). "AXL expression in NB cells and tumours with a mesenchymal signature was higher than in tumours with adrenergic signature; however, AXL expression does not drive adrenergic-to-mesenchymal transition in NB cells." (PMID 41511287, 2025). "Some more research has shown that MERTK, AXL, and other TAM receptors may help the immune system work better by using natural processes inside tumour cells, like making more PD-L1 appear on tumour cells." (PMID 40088262, 2025). "More critically, treatment with ZAXL:239 significantly reduced tumour growth in the mice bearing AXL-positive GC cell xenografts model and no significant side effects of ZAXL:239 drug treatment were observed." (PMID 39644434, 2025). "Furthermore, AXL and MER signalling induces expression of PD-L1 and PD-L2 (Programmed death-ligand 1 and 2) immune checkpoint proteins in tumour and myeloid cells inhibiting T-cell anti-tumour activity." (PMID 40044635, 2025). "Ultimately, we found that ECGs presented different profiles across 20 cancer types, with CD47 and TYRO3 more frequently exhibiting copy number increases rather than losses in the majority of tumours, while AXL and HAVCR1 showed a relatively opposite trend." (PMID 40576208, 2025). "Analysis of the Pan-Cancer dataset integrating International Cancer Genome Consortium (ICGC) and The Cancer Genome Atlas (TCGA) further revealed a significant correlation between FRA1 levels and AXL, CDK6, and FSCN1 expression in 1210 tumor samples of all cancer types." (PMID 41286309, 2025). "For instance, the human papillomavirus type 16E6 (HPV16E6) oncoprotein has been shown to upregulate AXL expression in cervical cancer via the MAGI-2/PTEN/Akt/MZF1 network, increasing tumor invasiveness and promoting immune evasion by reducing responsiveness to NK cells-mediated lysis." (PMID 39924521, 2025). "Multiplex IHC showed that T cells were restricted in the tumor stroma of FR‒ tumors, in combination with elevated tumor WNT-TGF and AXL programs by bulk RNA-seq analysis, supporting that cross-linking fibers may inhibit T cell infiltration in FR‒ tumors." (PMID 39870619, 2025). "This study suggests that AXL inhibition with tilvestamab does not lead to measurable anti-tumour responses in patients with PROC." (PMID 40696160, 2025). "In the TCGA-ccRCC cohort, the mRNA expression level of AXL was significantly elevated in tumor tissues compared to normal kidney tissues." (PMID 41029360, 2025). "Finally, we validated that co-inhibition of AXL and SRC significantly reduced tumor growth in A549 xenografts." (PMID 39941857, 2025). "In addition, other studies have combined AXL inhibitors, which inhibit dendritic cells, increase the number of TCF1+ CD8+ T cells in the tumour microenvironment and restore the PD‐1 blockade sensitivity of STING‐inhibited LKB1‐mutant NSCLC." (PMID 39592436, 2024). "Our patient cohort also shows that immunotherapy-induced changes in the abundance of AXL+ or MITF+ tumor cells did not correlate with improved survival." (PMID 39697983, 2024). "In the present study, we observed expression of AXL but not phospho‐IGF‐1R in tumor specimens obtained at both initial biopsy as well as operation in two patients." (PMID 38323355, 2024).
tumor (continued). "Cabozantinib, as a multitargeted receptor tyrosine kinase (RTK) inhibitor, acts upon Mesenchymal Epithelial Transition Factor (MET), VEGFR, and AXL receptor tyrosine kinase (AXL), thereby hindering tumor cell growth and angiogenesis while concurrently modulating the tumor microenvironment." (PMID 38443363, 2024). "Recognizing that U87MG cells are not necessarily a high-fidelity model of GBM because of long passage time and issues related to identification of the tumor of origin, these results are suggestive of the therapeutic potential of combination inhibition of S6K1 and AXL." (PMID 39087397, 2024). "Therefore, activation of the HGF-MET and GAS6-AXL pathways promotes tumor survival, proliferation, infiltration, and metastasis, and blocking VEGF can lead to MET and AXL activation." (PMID 38289361, 2024). "This hypothesis is supported by the elevated expression of AXL and MET reported in RCC cell lines chronically treated with sunitinib, and inhibiting AXL and MET led to tumor size reductions in xenograft models with acquired resistance to sunitinib." (PMID 39168901, 2024). "This hypothesis is consistent with tumor suppressive effects observed with treatment combinations targeting VEGFR2, MET, and AXL in RCC cancer cell lines and mouse xenograft models." (PMID 39168901, 2024). "Additionally, hub genes such as AXL and EZH2 were also found to be responsible for tumor growth and anti-neoplastic drug resistance/sensitivity." (PMID 36715825, 2023). "Moreover, 17 CRNGs were upregulated in tumor tissues, while only AIM2, AXL, and TLRL4 were downregulated." (PMID 37287752, 2023). "Specifically, our findings support a model in which YAP:TEAD-mediated transcription activates an AXL- and EGFR-initiated signaling cascade resulting in the activation of mTOR in epithelial cells, thus representing an actionable target to prevent tumor initiation." (PMID 37961717, 2023). "Double staining of AXL and OCT4 revealed that OCT4-positive stem cells are significantly reduced in GAS6-CAR-T group, thereby indicating that GAS6-CAR-T can target CSCs in vivo to enhance tumor clearance in consistent with the in vitro effects on CSCs." (PMID 37475048, 2023). "At baseline, immunohistochemical analysis showed that 16 of 17 evaluated tumor cell samples were negative for AXL, and 1 showed AXL‐positive staining in around 60% of tumor cells." (PMID 36621830, 2023). "In addition to its role in the development of tumor resistance, MITF acts as a master regulator of melanocyte differentiation through the upregulation of receptor tyrosine kinases (RTKs) including the AXL, EGFR, and PDGFRβ." (PMID 37370757, 2023). "Moreover, the tumor growth was significantly inhibited with a tumor growth inhibition rate of 86.7% and the expression level of YAP, AXL, EGFR, AKT, and ERK in the tumor tissue was decreased by Polymer@Gef-YAP-siRNA with laser." (PMID 37415158, 2023). "In conclusion, our study provides, for the first time, absolute quantification of RTKs in liver tissue from healthy individuals and cancer patients with a focus on CRLM, reflecting a significant suppression of EGFR, INSR, VGFR3, and AXL, and upregulation of IGF1R, EPHA2 and PGFRB in tumour." (PMID 36890818, 2023). "Consistent with the idea that there are common mediators of resistance to therapies regardless of tumor type, this case highlights the potential for AXL to also drive intrinsic resistance to ROS1 inhibitors in NSCLC." (PMID 37727007, 2023). "Even if some expression has been described on smooth muscle cells and other cells, there is no current evidence of toxicity induced by off-tumor AXL targeting." (PMID 37143061, 2023). "In tumours, CSF1R correlated with AXL, EPHA2 with PGFRA, and NTRK2 with PGFRB and AXL." (PMID 36890818, 2023).
tumor (continued). "It has been shown that co-implantation of human umbilical vein endothelial cells (HUVECs) overexpressing AXL with HCC cells in xenograft nude mice and patient-derived xenograft (PDX) nude mice substantially enhanced tumor growth, hepatic metastasis, and vessel metastasis of HCC." (PMID 37469409, 2023). "Thus, apart from impairing VEGF signalling, cabozantinib inhibits a variety of receptor tyrosine kinases including MET and TAM kinases (TYRO3, AXL, MER) involved in tumour growth, metastasis, and therapeutic resistance with a role in immunosuppression." (PMID 35106125, 2022). "Importantly, the numbers of CD8+ CAR T cells, known as a major population of tumour-killing cells, were higher owing to MWA in the combination group than in the AXL-CAR T monotherapy group." (PMID 36261437, 2022). "AXL inhibition resulted in a dramatic suppression of Tregs in the TC1 tumor model but produced a less effective or not significant effect in the C3PQ model." (PMID 35356198, 2022). "We have shown here that a 14FN3 based library of 25 billion Pronectin variants is a viable source of non-antibody protein binders that can recognize tumor cells receptors, like AXL tumor receptor, in a very specific and selective way." (PMID 36551940, 2022). "The connection revealed here between AXL and WNK1 raises the possibility that WNK1 may be a therapeutic option in other AXL-dependent tumor types as well." (PMID 35813203, 2022). "Notably, the combination of MWA and AXL-CAR T cells yielded a synergistic effect, which enhanced T cell killing capability and prevented distant metastasis in CDX tumour models." (PMID 36261437, 2022). "AXL behaved as a cancer-promoting gene in our sample validation due to its overexpression in tumor tissues and its negative connection with survival time." (PMID 36186479, 2022). "In particular, the beneficial collaboration between drugs seems to boost immunosurveillance mechanisms in the tumour microenvironment, modulated mainly through simultaneous PD1 blockade and inhibition by cabozantinib of Tyro3/AXL/MER (TAM) receptors and VEGFR1." (PMID 35106125, 2022). "We found that the levels of cytokines, including IL-2, IFN-γ and TNF-α, were very low in tumours treated with AXL-CAR T cell monotherapy, suggesting that mono-CAR T cells were hypofunctional and/or that the absolute number of AXL-CAR T cells responding to the tumour cells was low." (PMID 36261437, 2022). "Interaction between GAS6 expressed by CAFs and AXL expressed by myeloid cells changes the interaction levels of PD-L1 and MHC-I, increases the secretion of cytokines involved in immune suppression, and decreases the tumor-infiltrating CTL population." (PMID 35892844, 2022). "Given the increasing evidence of AXL implication in EMT and the deregulation of the tumor microenvironment, this RTK may be an interesting candidate for the prediction of disease progression including metastasis, relapse, and therapy response." (PMID 35158733, 2022). "Furthermore, in the C3PQ tumor model, the effector memory subset of CD8+ T cells was continuously increased by the initial inhibition of AXL (***p<0.001)." (PMID 35356198, 2022). "In the present study, we observed that the expression of integrin β3 and AXL was significantly upregulated in erlotinib-resistant NSCLC cell lines, which was further confirmed clinically in tumor specimens from patients with NSCLC who developed acquired resistance to erlotinib." (PMID 35805163, 2022). "In summary, the GAS6/AXL signaling may promote macrophage, monocyte, and MDSC infiltration, decrease tumor abundance of mature DCs, NK CD4+ and CD8+ T-cells." (PMID 35572601, 2022). "In EGFR TKI-resistant tumor xenografts, the expression level of AXL was found to be elevated, and inhibition of AXL recovered the sensitivity to EGFR-TKI, which implies that activation of AXL is essential for acquired resistance to EGFR-TKI in NSCLC." (PMID 35805163, 2022).